IL4R (interleukin 4 receptor)
Diseases named in the same sentence as IL4R in open-access papers (continued):
Sharing a sentence is not in itself a finding about the gene and the disease.
cancer (71 papers, 1989 to 2025). A tumor composed of atypical neoplastic, often pleomorphic cells that invade other tissues. "In contrast, mice deficient in IL-4R in the granulocyte-monocyte progenitors exhibited poorer cancer growth than wild-type mice and had much smaller numbers of mo-mac in cancer, suggesting that IL-4 signaling is a prerequisite for the development of MDCSs." (PMID 38474078, 2024). "These clinical impact of the IL4Rα and IL13Rα1 expression in human cancer has been associated with the role of IL4Rα/IL13Rα1 receptor complex in the proliferation and survival of cancer cells." (PMID 33419470, 2021). "The individual and co-expression patterns of IL4Rα and IL13Rα1 were significantly associated with cancer-specific survival (CSS) and relapse-free survival (RFS) in univariate analysis." (PMID 31540495, 2019). "It has been reported that receptors for IL4 and IL13 (IL4Rα or IL13Rα1) in several type of cancers is associated with poor prognosis and thus could be therapeutic targets of cancer treatment." (PMID 35207737, 2022). "Collectively, these findings suggest that IL4R-targeted Abx has a broad spectrum of applications in the management of patients with cancer." (PMID 38646639, 2024). "This study aimed to enhance Abx delivery to IL4R-high M2-type macrophages via the surface modification of Abx with IL4RPep-1 and reprogramming of M2-type macrophages into M1-like phenotype for cancer immunotherapy." (PMID 38646639, 2024). "The interaction network of 50 SHP-1-binding proteins showed that many of them were involved in immune function and cancer signal transduction, such as IL4R, JAK1, CD33." (PMID 39367146, 2024). "Altogether, the current study suggests that IL4R-targeted Abx presents as a promising cancer immunotherapeutic agent targeting M2 macrophages." (PMID 38646639, 2024). "Both IL-4Rα and IL13-Rα1 have also been implicated in cancer progression and were recently identified as prognostic indicators in soft-tissue sarcoma patients when present in the nucleus." (PMID 38577257, 2023). "Interleukin-4 (IL-4) and its receptors (IL-4R) are crucial in cancer cell proliferation and other biological behaviors like migration and invasion." (PMID 37117331, 2023). "IL4RPep-1-EVs were rapidly internalized by Cal-62 cells compared to NSSSVDK-EVs, which were internalized at a relatively low level, up to 60 min post-incubation, confirming the ability of IL4RPep-1-EVs to target IL4R-expressing Cal-62 cancer cells." (PMID 36009525, 2022). "In line with this study, the role of the expression of IL4Rα and IL13Rα1 as prognostic indicator has been reported in various human cancers." (PMID 35207737, 2022). "The cut-off points have the highest area under the curve (AUC) to predict cancer-related death of patients, and the cut-off points for Nu-IL4Rα, Cy-IL4Rα, Nu-IL13Rα1, and Cy-IL13Rα1 were 8, 11, 9, and 14, respectively." (PMID 35207737, 2022). "Many studies suggest IL-4R as an effective target for cancer therapy, and it is in use in clinics for treating different types of cancer." (PMID 36009525, 2022). "We identified CXCR2 as an important downstream factor from IL4Rα that promotes extravasation of cancer cells in vitro." (PMID 36077870, 2022). "Our results indicate the labeling of EVs with IL4RPep-1 is a promising strategy for the therapeutic application of EVs and/or drug delivery EVs that target IL4R-expressing cancers." (PMID 36009525, 2022). "Higher expression of IL4Rα and IL13Rα1 was observed in various types of human cancers such as colorectal, breast, pancreatic, bladder, brain, and ovarian cancers." (PMID 33419470, 2021). "The existence of high IL-4R immunoreactivity was detected in the ductal cancer cells in 40% (28 of 70) of primary PDAC samples." (PMID 33804263, 2021). "The prognostic impact of the expression of IL4Rα and IL13Rα1 in human cancers is related to the role of IL4Rα/IL13Rα1 in cancer-related signaling." (PMID 33419470, 2021).
cancer (continued). "The activation of IL4Rα/IL13Rα1 by IL4/IL13 stimulates JAK1/JAK2/JAK3-STAT6-mediated proliferation of cancer cells." (PMID 33419470, 2021). "On the other hand, it is appealing to test the safety and efficacy of combining dupilumab with checkpoint blockade therapy to treat cancers of epithelial origin that express high levels of IL4Rα in tumor cells." (PMID 34235145, 2021). "Recently, IL4Rα and IL13Rα1 were reported to have roles in cancer progression and suggested as potential prognostic markers." (PMID 33419470, 2021). "Cell Viability and luciferase assay of 4T1-Luc2 cancer cells in the presence of anti-VCAM-1 ssDNA or anti-IL4Rα RNA aptamers was assessed by monitoring the changes in the absorbance and the fluorescence of Alamar blue dye." (PMID 32751068, 2020). "Nonetheless, functional studies regarding other epithelial cancers have shown IL-4Rα to facilitate the proliferation and survival of cancer cells at metastatic sites." (PMID 32512917, 2020). "The functional overexpression of IL4Rα and its ligand on several human cancer cells has been the rationale for generating immunotoxins targeting IL4R and IL13R." (PMID 32957689, 2020). "IL-4 and IL-13 per se exert a protumor function, since they directly bind to high-affinity receptors (IL-4Rα and IL-13Rα1 chains), forming functional receptors in cancer cells." (PMID 33233582, 2020). "On the other hand, putative M-MDSCs showed greater abundance of transcripts encoding both the IL4R, consistent with previous data, and S100A8, serum concentrations of which have been associated with poor cancer survival." (PMID 30837603, 2019). "IL-4 is thought to be controversial for cancer therapy because multiple forms of cancer express the IL-4R." (PMID 30842774, 2019). "The type II IL-4R, composed of the two subunits IL-4Rα and IL-13Rα1, is the predominant complex in cancer cells." (PMID 28927416, 2017). "Expression of IL-4 and IL-4Rα proteins was upregulated by IR treatment in various cancer cell lines, including MCF-7, MDA-MB-231, A498, Caki-1, and HEK-293 cells, suggesting that this phenomenon is generalizable." (PMID 27895317, 2016). "We found that interleukin-4 (IL-4) and IL-4Rα (IL-4 receptor) are highly expressed in various human cancer cells subsequent to radiation treatment." (PMID 27895317, 2016). "Increased expression of IL-4 and IL-4 receptor (IL-4Rα) has been reported in several cancer cell types, including breast, ovarian, colon, lung, and thyroid cancers." (PMID 27895317, 2016). "The expression of IL-4Rα mediates the action of IL-4, so we performed the Western blot analysis to investigate the IL-4Rα expression of various cancer cells." (PMID 26993600, 2016). "We previously reported that IL-4Rα-lytic had effective cytotoxic activity toward cancer cells expressing IL-4Rα and that enhancement of the IL-4Rα-lytic peptide-induced cytotoxicity correlates well with the expression levels of IL-4Rα." (PMID 24868471, 2014). "KMBC and CCKS-1 cell lines showing higher levels of IL-4Rα expression showed higher sensitivity (IC50 of IL-4Rα-lytic hybrid peptide toward these cancer cells was approximately 2 μM)." (PMID 24868471, 2014). "The studies have revealed that the incorporation of multivalent targeting peptide ligand into ELP polymer facilitated the greater targeting to IL-4R expressing cancer cells." (PMID 24339977, 2013). "Although the receptor for interleukin-4 (IL-4R) is highly expressed on solid human cancer cells, its internalization function is still unclear." (PMID 23029030, 2012). "Immunohistochemical analysis of a wide range of solid tumours using monoclonal antibody MR6 has demonstrated elevated expression of the IL-4R on a variety of carcinomas." (PMID 2736228, 1989). "Interestingly, effector activity of D7 CAR T cells, but not C4 CAR T cells, was demonstrated when cocultured with IL13Rα1/IL4Rα-coexpressing cancer cells." (PMID 35939683, 2022).
cancer (continued). "However, the low micromolar affinity was not sufficient to decrease D7 CAR T cell response to IL13Rα1/IL4Rα-overexpressing cancer cells." (PMID 35939683, 2022). "Interestingly, C4, but not D7, showed attenuated cytotoxicity relative to WT against IL13Rα1/IL4Rα-coexpressing cancer cells in vitro and in vivo." (PMID 35939683, 2022). "Additionally, several cancer types express IL-4 and the IL-4R, which suggests a role in tumor progression cancer." (PMID 36172343, 2022). "In addition, the prognostic significance of individual expression of IL4Rα or IL13Rα1 has been reported in various human cancers." (PMID 33419470, 2021). "Therefore, although most reports suggest the IL4R complex as a promising therapeutic target of human cancers, a tailored approach according to the specific subtype of cancer is likely to be the most effective." (PMID 33419470, 2021). "A new potential treatment modality for cancer could be dupilumab, an antibody targeting IL4Rα, a receptor subunit for IL4 and IL13." (PMID 34235145, 2021). "However, despite the presence of cytoplasmic and nuclear expression of IL4Rα and IL13Rα1 in human cancers, there have been no reports specifically focused on the effects of subcellular localization of IL4Rα and IL13Rα1 in human cancers." (PMID 33419470, 2021). "Especially, the IL4 receptor (IL4R) complex has been studied for its role in cancer progression." (PMID 33419470, 2021). "Therefore, further study is needed to clarify the role of cytoplasmic and nuclear expression of IL4Rα and IL13Rα1 in human cancers." (PMID 33419470, 2021). "Interestingly, an IPA analysis showed that different regulated genes were positively associated with the invasion and migration process in cancer cells: VCAN, SPARC, IL6, MMP14, IL4R, ICAM, TIMP1 and IGF2." (PMID 32848147, 2020). "IL4 and IL13 bind to IL4Rα and IL13Rα1 chains, forming functional structures in cancer cells." (PMID 31540495, 2019). "However, since both adipose tissue and cancer cells secrete IL-4 to promote a suppressive tumor microenvironment, blocking IL-4R signaling was found to decrease the viability of breast tumor cells." (PMID 30842774, 2019). "However, fractionation of these rare cell populations revealed that stem-like cells isolated from cancers have significantly higher expression levels of IL4Rα, suggesting a potential tumourigenic role for IL-4/IL4Rα in PCa CSCs." (PMID 28553931, 2017). "Additionally, MATK has been related to cell invasion and IL4R expression in cancer cells seems to facilitate lymph node metastasis." (PMID 29285214, 2017). "To see whether IL-4R expression could be related to an anti-cancer effect of IL-4, we investigated the IL-4R expression pattern in several cancer cell lines." (PMID 26993600, 2016). "IL-4 and IL-4Rα were also highly expressed in several types of cancer cells (right)." (PMID 27895317, 2016). "Previous reports have suggested that IL-4 could either promote or inhibit cancer cell proliferation in vitro by exerting effects through binding to IL-4R expressed on cancer cells." (PMID 27563494, 2015). "Although the biological significance of IL-4Rα expression of cancer cells remains unclear, this receptor is a candidate applicable for molecular targeted cancer therapy." (PMID 24868471, 2014). "It is suggested that the inhibition effect by gemcitabine in cancer cells might be exerted synergetically with the disintegration activity toward cancer cell membrane by IL-4Rα-lytic hybrid peptide." (PMID 24868471, 2014). "Initially, it was hypothesised on the basis of upregulation of IL-4R molecules in malignant tumours of epithelial origin that IL-4R may be a product of an oncogene that could be involved in the process of carcinogenesis." (PMID 15714203, 2005). "Additionally, IL-4R promoted cancer cell resistance to chemotherapy drugs in colorectal cancer." (PMID 37117331, 2023).
cancer (continued). "Thus, not only the distinct expression levels of respective receptor chains, but also the ratio between IL-13Rα1 and IL-4Rα expression may be crucial for the effect of IL-4 and IL-13 on the cancer cell phenotype." (PMID 35409019, 2022). "Interestingly, coexpression of IL13Rα1 or IL4Rα in cancer cells caused both E12Y and D7 CAR T cells, but not C4 CAR T cells, to respond comparably to WT CAR T cells in vitro." (PMID 35939683, 2022). "The carcinoma positive for Nu-IL4Rα had a 4.614-fold (95% CI (95% confidential interval); 2.575–8.269) greater risk of death and a 4.019-fold (95% CI; 2.311–6.988) greater risk of relapse or death compared with carcinoma negative for Nu-IL4Rα." (PMID 35207737, 2022). "Therefore, targeting the IL4R complex might be a therapeutic strategy for cancers with poor prognosis that highly express IL4Rα and IL13Rα1." (PMID 33419470, 2021). "Therefore, it is suggested that the nuclear localization of IL4Rα and IL13Rα1 might have a role in the progression of cancers." (PMID 33419470, 2021). "Therefore, IL4Rα and IL13Rα1 might be an effective therapeutic target of various human malignant tumors." (PMID 31540495, 2019). "Pre-incubation of cancer cells with IL-4Rα blocking antibodies alone did not significantly affect control/unstimulated cell preparations." (PMID 40091029, 2025). "ECD, IL4R and WDR82 are protein coding genes, not commonly known to be associated with cancer risk or prognosis." (PMID 35444210, 2022). "Our anti-MUC1-CAR4 T cells showed potent anti-cancer effect comparable to that of other studies in different cancer models using second- and third-generation anti-MUC1-CAR T cells, and also inverted cytokine receptor (IL-4R/IL-7) CAR T cells." (PMID 33737613, 2021). "Another TNBC cancer cell line, E0771, also showed sensitivity to the fusion toxin albeit with a slightly higher IC50 value of 4 nm, a difference potentially attributable to different IL‐4R expression levels and/or growth rates." (PMID 33682324, 2021). "As IL-4R is overexpressed in different types of the solid tumor, we believed that these AP1-ELPs would provide a promising platform for targeted therapy of various cancers." (PMID 32190533, 2020). "In addition, based on the molecular relationship between IL4Rα and IL13Rα1 as components of the type II IL4R complex and their possible roles in cancer progression, we evaluated the prognostic significance of the co-expression pattern of nIL4Rα and nIL13Rα1 in STSs." (PMID 33419470, 2021). "However, the significance of the nuclear localization of IL4Rα and IL13Rα1 in the progression of cancer is not clear." (PMID 33419470, 2021). "Furthermore, IL-4R is expressed at significantly higher levels in cancerous tissues compared to normal tissues Additionally, reducing IL-4R expression in HCC cells resulted in increased cell death, decreased growth, and lowered invasiveness of these cancer cells." (PMID 40544399, 2025).
inflammation (13 papers, 2010 to 2025). Aberrant reaction of the microcirculation characterized by movement of fluid and leukocytes from the blood into extravascular tissues. "There are case reports of therapeutic success using the anti-IL4Rα monoclonal antibody dupilumab to control eosinophilic GI inflammation in HIES patients." (PMID 36211419, 2022). "Previous studies have indicated that IL‐13/IL‐4Rα signalling pathway is involved in the amplification and polarization of the alveolar and bone marrow–derived macrophages, resulting in airway inflammation." (PMID 33305406, 2021). "By contrast, alternatively activated macrophages are defined by tissue expression of Arg1 and other markers, such as Ym1, Fizz1, and the IL-4Rα-subunit especially during pulmonary inflammation." (PMID 29176982, 2017). "These cells produced In addition, unlike OVA-exposed wild-type mice with mixed neutrophilic and eosinophilic inflammation, OVA treatment of IL-4R KO mice induced airway inflammation which was almost exclusively neutrophilic in character." (PMID 24907978, 2014). "The data further suggest that in the absence of macrophage-specific IL-4Rα signalling, IL-10 is able to drive mannose receptor- and Ym1-positive macrophages, associated with control of hepatic granulomatous inflammation." (PMID 20502521, 2010). "Also, the IL‐13/IL‐4Rα signalling pathway is involved in the amplification and polarization of the alveolar and bone marrow–derived macrophages, thus promoting the development of airway inflammation." (PMID 33305406, 2021). "In contrast to OVA-treated wild-type mice with both neutrophilic and eosinophilic airway inflammation, OVA-treated IL-4R KO mice showed increased neutrophilic inflammation with few eosinophils in the airways." (PMID 24907978, 2014). "Recent advancements in COPD treatment have introduced biologic agents such as Dupilumab (anti-IL-4Rα monoclonal antibody), Ensifentrine (a dual PDE3/4 inhibitor), and anti-IL-33 therapies, which have shown promise in controlling airway inflammation, particularly in patients with type 2 inflammation." (PMID 40333888, 2025). "In the absence of IL-4Rα responsiveness on FoxP3+ Tregs, exacerbated AHR and airway inflammation were shown in HDM-sensitized mice." (PMID 32931477, 2020). "Unlike responses in the small intestine, the absence of Il4ra on T reg cells only modestly reduced the frequency of ex-Foxp3 Th2 cells, suggesting that IL-4R–independent mechanisms also contribute to T reg cell conversion after acute HDM-driven airway inflammation." (PMID 28507062, 2017).
bacterial infection (4 papers, 2020 to 2025). "During a bacterial infection, Th2-associated cytokine IL-4, by binding to the IL-4 receptor (IL-4R), can suppress neutrophil recruitment to the site of inflammation." (PMID 39767651, 2024). "However, in AD patients, we found that IL-4R-targeted biologics—dupilumab—were associated with a decreased risk of bacterial infection (OR: 0.23 [0.06–0.92])." (PMID 41303888, 2025). "Bacterial infections were found to be decreased in AD patients who had received dupilumab (IL4R-targeted biologic)." (PMID 41303888, 2025).
lung (3 papers, 2010 to 2022). "Future investigation may clarify whether IL-10-driven IL-4Rα-independent MMR+Ym1+ macrophages have important functions in the control of liver granulomatous inflammation." (PMID 20502521, 2010).
infectious disease (2 papers, 2017 to 2023). A disorder directly resulting from the presence and activity of a microbial, viral, or parasitic agent in humans. "Another candidate, IL4R, encoding the alpha chain of the interleukin-4 receptor that can bind IL4 and IL13, has not been previously reported to be associated with infectious diseases." (PMID 37033939, 2023).
neurodegenerative disease (2 papers, 2020 to 2022). A disorder of the central nervous system characterized by gradual and progressive loss of neural tissue and neurologic function. "The IL-4/IL-4Rα-Nrf2 axis maybe the potential targets for the development of novel therapies for neurodegenerative diseases." (PMID 36539414, 2022).
respiratory disease (2 papers, 2024 to 2025). "A blockade of IL-4R can alleviate symptoms of respiratory disease by decreasing the serum levels of IgG4/IgE." (PMID 40005151, 2025).
intestinal diseases (1 paper, 2020). "Although further detailed studies are required, the role of IL-4Rα in the intestinal inflammation revealed here may improve the understanding of the pathogenesis of refractory intestinal diseases such as IBD." (PMID 33192516, 2020).
peripheral neuropathy (1 paper, 2025). A disorder affecting the peripheral nervous system. "However, because UP has numerous potential pruritogens, such as toxins, Th1 cells, and peripheral neuropathy, and because dupilumab only targets IL-4Rα, its antipruritic effect on UP remains to be observed, and the sample size needs to be expanded." (PMID 41001391, 2025).